SPMIP6 (sperm microtubule inner protein 6)
Description:
May participate in intramanchette transport and midpiece formation of the sperm tail. May play a potential role in somatic cell proliferation.
Synonyms: C9orf24; CBE1; SMRP1; bA573M23.4; NYD-SP22; MGC32921; MGC33614
Tractability: No criterion of Open Targets' tractability assessment is met for any kind of drug.
Gene: Protein-coding gene on chromosome 9 (34,379,019 to 34,397,828, reverse strand). Ensembl gene ENSG00000164972.
Subcellular location: Cytoplasm, cytoskeleton; Nucleus; Cytoplasm; Mitochondrion; Cytoplasm, cytoskeleton, flagellum axoneme
Subcellular location (Human Protein Atlas): Nucleoplasm; Principal piece; Cytosol; Equatorial segment
Gene Ontology:
Molecular function: protein binding; alpha-tubulin binding
Biological process: flagellated sperm motility
Cellular component: cytoplasm; cytosol; nucleoplasm; nucleus; perinuclear region of cytoplasm; sperm principal piece; manchette; mitochondrion; sperm midpiece; axonemal A tubule inner sheath; cytoskeleton; sperm flagellum
Genetic constraint (gnomAD): Loss-of-function variants: 17 observed, 32.94 expected, observed/expected ratio (o/e) 0.52, 90% interval 0.35 to 0.77. The upper end of that interval is the gene's LOEUF score, 0.77, which puts it in group 3 of 6, group 1 being the genes least tolerant of losing a copy. Missense variants: 335 observed, 351.22 expected, observed/expected ratio (o/e) 0.95, 90% interval 0.87 to 1.04. Synonymous variants: 123 observed, 135.9 expected, observed/expected ratio (o/e) 0.91, 90% interval 0.78 to 1.05.
Homologues: Orthologues: chimpanzee SPMIP6 (99% identical), macaque SPMIP6 (97% identical), pig SPMIP6 (81% identical), dog SPMIP6 (80% identical), mouse Spmip6 (76% identical), guinea pig SPMIP6 (73% identical), rat Spmip6 (72% identical).
Diseases named in the same sentence as SPMIP6 in open-access papers:
SPMIP6 is named in the same sentence as 3 diseases in open-access papers, as found by Europe PMC text mining. Sharing a sentence is not in itself a finding about the gene and the disease.
SPMIP6 shares sentences with these, for which no sentence is quoted: cancer (1 paper); infection (1); lung carcinoma (1).